SYK (spleen associated tyrosine kinase)
Diseases named in the same sentence as SYK in open-access papers (continued):
Sharing a sentence is not in itself a finding about the gene and the disease.
neuroblastoma (continued). "Moreover, we demonstrate that SYK is present in neuroblastoma tissues and to a lesser extent in neuroblastoma cell lines." (PMID 30744170, 2019). "We determined the status of these three well-established SYK phosphorylation sites (Tyr352, Tyr525/526, and Tyr323) and found that all were phosphorylated under normal growth conditions in the SYK expressing SH-SY5Y neuroblastoma cells, suggesting the presence of catalytically active SYK." (PMID 30744170, 2019). "However, SYK protein was detected by western blotting in only two of 10 neuroblastoma cell lines, even after long exposure times." (PMID 30744170, 2019). "In addition, we also demonstrate that transient transfection with a constitutively active SYK variant increased the cell viability of neuroblastoma cell lines independent of endogenous SYK expression." (PMID 30744170, 2019). "To determine whether SYK exhibits basic activity in neuroblastoma cell lines, we performed SYK immunoprecipitation followed by western blot with different phosphotyrosine-specific SYK antibodies in SH-SY5Y cell lysates and THP-1 cells, serving as a positive control." (PMID 30744170, 2019). "Our findings demonstrate the presence of functional SYK in neuroblastoma tissue as well as certain neuroblastoma cell lines and indicate that pharmacological SYK inhibition may be a potential therapeutic approach that can be used to support conventional chemotherapy in SYK-expressing neuroblastomas." (PMID 30744170, 2019). "However, additional studies are necessary to determine if known factors, such as specific cytokines and chemokines, present in the neuroblastoma tumor microenvironment may affect SYK expression and function." (PMID 30744170, 2019). "Therefore, one could speculate that the absence of a specific stimulus, which is present in the tumor microenvironment, could lead to the downregulation of SYK expression in neuroblastoma cells lines." (PMID 30744170, 2019). "Therefore, the presence of specific stimuli in the neuroblastoma tumor microenvironment as well potential differences/changes in SYK splicing pattern compared to neuroblastoma cell lines may contribute to the observed differences in staining pattern." (PMID 30744170, 2019). "Taken together, this suggests that SYK functions as a tumor-promoting molecule in neuroblastoma rather than having a tumor-suppressing effect." (PMID 30744170, 2019). "Therefore, we investigated the effects of commercially available SYK inhibitors BAY 61-3606, R406, PRT062607 (P505-15) and GS-9973 on neuroblastoma survival." (PMID 30744170, 2019). "Spleen tyrosine kinase (SYK) has previously been identified as a promising drug target in various inflammatory diseases and cancers but has so far not been extensively studied as a potential therapeutic target in neuroblastoma." (PMID 30744170, 2019). "Additionally, SYK inhibition decreased phosphorylation of Akt and ERK1/2 indicating Akt and MAPK signaling as potential downstream targets of SYK in neuroblastoma." (PMID 30744170, 2019). "Of note, by examining publicly available gene expression datasets, we detected a negative correlation between MYCN and SYK in neuroblastoma." (PMID 30744170, 2019). "Therefore, a potential connection between SYK and MYC in neuroblastoma is highly interesting and warrants further investigation." (PMID 30744170, 2019). "Furthermore, constitutive active SYK increased neuroblastoma cell viability independent of endogenous SYK expression." (PMID 30744170, 2019).
non-Hodgkin lymphoma (2 papers, 2019 to 2021). Distinct from Hodgkin lymphoma both morphologically and biologically, non-Hodgkin lymphoma (NHL) is characterized by the absence of Reed-Sternberg cells, can occur at any age, and usually presents as a localized or generalized lymphadenopathy associated with fever and weight loss. "SYK inhibition has been shown to reduce the viability of Non-Hodgkin lymphoma cells by disruption of BCR signaling." (PMID 31645904, 2019). "In the future, inhibition of GCN5 as well as SYK with targeted drug therapies may provide a synergistic therapy for Non-Hodgkin lymphoma." (PMID 31645904, 2019).
non-small cell lung carcinoma (2 papers, 2016 to 2023). A group of at least three distinct histological types of lung cancer, including non-small cell squamous cell carcinoma, adenocarcinoma, and large cell carcinoma. "The decreased expression of SYK was inversely correlated with the survival of non-small-cell lung cancer." (PMID 37279937, 2023).
osteoporosis (2 papers, 2020 to 2024). A condition of reduced bone mass, with decreased cortical thickness and a decrease in the number and size of the trabeculae of cancellous bone (but normal chemical composition), resulting in increased fracture incidence. "In comparison to the SOP group, the SOP+Lv-sh-SHP2 group exhibited significantly reduced levels of p-NF-κB, p-SHP2, and t-SHP2, while p-SYK levels remained unchanged, suggesting that SYK’s influence on osteoporosis might be upstream of the SHP2 pathway." (PMID 39197167, 2024). "SYK may influence the balance of bone remodeling by regulating the activity of macrophages and other skeletal cells, thereby affecting bone density and the development of osteoporosis." (PMID 39197167, 2024). "SYK’s entanglement in bone resorption suggests its potential regulatory oversight over macrophages and other osseous cells, which might upset the homeostasis of bone remodeling, influencing bone density, and contributing to osteoporosis’s evolution." (PMID 39197167, 2024). "In synergy with RANKL, glucocorticoids potentiate osteoclastogenesis via the SYK/SHP2/NF-κB cascade, hence hastening osteoporosis’ advancement." (PMID 39197167, 2024). "To investigate how macrophage-specific knockout of SHP2 affects the mechanisms of osteoporosis, we examined the protein expression levels of tyrosine kinase SYK (Spleen Tyrosine Kinase) and transcription factor NF-κB." (PMID 39197167, 2024). "To encapsulate, the potent symbiosis between glucocorticoids and RANKL energizes the SYK/SHP2/NF-κB pathway, endorsing bone marrow monocyte differentiation into osteoclasts and precipitating the advance of osteoporosis." (PMID 39197167, 2024). "Harmonizing with glucocorticoid receptors and RANKL, SHP2 ignites the SYK/SHP2/NF-κB cascade, thus endorsing osteoclastogenesis and propelling osteoporosis progression." (PMID 39197167, 2024). "The collaborative activation by glucocorticoid receptors and RANKL within the BMMs from ovariectomized mice, through the SYK/SHP2/NF-κB cascade, abets osteoclast formation and promotes swift osteoporosis onset." (PMID 39197167, 2024). "The revelation of glucocorticoid receptors and RANKL’s collaboration in instigating the SYK/SHP2/NF-κB signaling nexus thus potentiating osteoclast genesis, unveils fresh vantages on the mechanisms whereby glucocorticoids promote osteoporosis." (PMID 39197167, 2024). "Our findings suggested that SOX6, ACE, SYK and TGFB3 may play important roles in the bone formation of osteoporosis in postmenopausal women." (PMID 32496000, 2020).
periodontal disease (2 papers, 2022 to 2025). "For the reason that Mφ polarization is a central event in both destructive and regenerative phases of periodontal disease, we tried to understand if Mincle/SYK was closely related to periodontal regeneration." (PMID 35251521, 2022).
Salmonella Infections (2 papers, 2016 to 2023). Infections with bacteria of the genus SALMONELLA. "In the context of Salmonella infection, it has also been reported that CARD9 negatively regulates IL-1β by fine-tuning pro-IL-1β expression, SYK-mediated NLRP3 activation and repressing inflammasome-associated caspase-8 activity." (PMID 37528097, 2023).
sarcopenia (2 papers, 2023 to 2025). Progressive decline in muscle mass due to aging which results in decreased functional capacity of muscles. "One of the innovative aspects of this research is the identification of the SYK gene as a risk factor for sarcopenia development in patients treated with fruquintinib." (PMID 40740773, 2025). "MR studies suggest that the spleen tyrosine kinase (SYK) gene is a key factor in the occurrence of sarcopenia associated with the use of fruquintinib." (PMID 40740773, 2025). "The SYK gene is considered to be the most likely candidate gene associated with an increased risk of sarcopenia." (PMID 40740773, 2025). "We identified SYK as a risk gene for fruquintinib-induced sarcopenia through MR analysis." (PMID 40740773, 2025). "In our study, MRC supercomplex formation is analyzed in C2C12 myoblastic cells in the context of potential application in sarcopenia treatment, which points to a potential role of SYK in MRC supercomplex formation in muscle tissue." (PMID 36697396, 2023). "SYK inhibitors may be applicable in the prevention and/or treatment of diseases or conditions in which skeletal muscle weakness is involved, such as sarcopenia, mitochondrial diseases, and muscular dystrophy." (PMID 36697396, 2023). "However, no studies have identified a correlation between the SYK gene and cancer-associated sarcopenia, indicating a need for further in-depth investigation in future research." (PMID 40740773, 2025).
silicosis (2 papers, 2022 to 2024). Silicosis is a respiratory disease caused by breathing in (inhaling) silica dust. "Using this comprehensive dataset, phosphorylated EGFR and SYK were found to play significant roles in silicosis progression by regulating the extracellular matrix and production of inflammatory cytokines." (PMID 35551173, 2022). "In our results, p-EGFR and p-SYK consistently increased with silicosis progression in the phosphoproteome data." (PMID 35551173, 2022). "Notably, our recent study revealed the aberrant pathways at protein phosphorylation levels in the lungs of silicosis mice and identified the phosphorylation of EGFR (p-EGFR) and SYK (p-SYK) as potential therapeutic targets in the progression of silicosis." (PMID 38641226, 2024). "Inhibition of p-EGFR and p-SYK by gefitinib and fostamatinib were found to effectively ameliorated the progression of silicosis via inhibiting p-EGFR mediated fibronectin production in fibroblasts and p-SYK mediated pro-inflammatory cytokines synthesis in macrophages." (PMID 35551173, 2022). "Notably, gefitinib and fostamatinib, inhibitors of p-EGFR and p-SYK, effectively attenuated silicosis, suggesting a promising strategy for silicosis." (PMID 35551173, 2022). "We further clarified the mechanisms of p-EGFR and p-SYK in the development of silicosis." (PMID 35551173, 2022). "Notably, the phosphorylation of EGFR (p-EGFR) and SYK (p-SYK) were identified as potential therapeutic targets in the progression of silicosis." (PMID 35551173, 2022).
Sjögren’s syndrome (2 papers, 2021). "This could further support the role of SYK inhibition in treatment of Sjögren’s syndrome." (PMID 33781343, 2021).
Splenomegaly (2 papers, 2018 to 2022). Abnormal increased size of the spleen. "Of note, the SYK inhibitor strongly prevented tumor-induced neutrophilia and splenomegaly in mice." (PMID 35453656, 2022).
stomach adenocarcinoma (2 papers, 2021 to 2023). "The low SYK expression (p = 2.895 × 10−3), NDRG1_pT346 (p = 3.872 × 10−2), P90RSK (p = 1.991 × 10−3), and TIGAR (p = 2.885 × 10−4) and the high XBP1 expression (p = 8.621 × 10−4) were significantly positively associated with the poor overall survival of STAD (stomach adenocarcinoma) patients." (PMID 36979962, 2023).
systemic candidiasis (2 papers, 2021 to 2022). "CLR/SYK-mediated negative regulation of macrophage function during systemic candidiasis also occurs." (PMID 34964702, 2022). "Specifically, the E3-ubiquitin ligase CBLB targets DECTIN-1, DECTIN-2, and SYK for ubiquitination and degradation in macrophages (and DCs) and leads to impaired inflammasome activation, oxidative burst, and fungal killing and increased mortality during systemic candidiasis." (PMID 34964702, 2022).
Thrombocytopenia (2 papers, 2021 to 2025). A reduction in the number of circulating thrombocytes. "Collectively, our findings suggest that specific targeting of PLT SYK might be a promising therapeutic approach to treat thrombocytopenia and thrombosis in VITT, and possibly in other Fc-RIIA–mediated immune thrombotic diseases." (PMID 39705541, 2025).
viral hepatitis (2 papers, 2021 to 2022). An acute or chronic inflammation of the liver parenchyma caused by viruses. "Conversely, antagonism of spleen tyrosine kinase (SYK) using pharmacological kinase inhibitors was shown to attenuate the progression of viral hepatitis." (PMID 33807722, 2021).
acute coronary syndrome (1 paper, 2025). Signs and symptoms related to acute ischemia of the myocardium secondary to coronary artery disease. "In patients with acute coronary syndrome (ACS), the expression of spleen tyrosine kinase (SYK) in monocytes may serve as a potential biomarker for predicting the risk of recurrent ischemic events." (PMID 40746537, 2025).
acute respiratory distress syndrome (1 paper, 2023). Progressive and life-threatening pulmonary distress in the absence of an underlying pulmonary condition, usually following major trauma or surgery. "Due to its ability to affect the SYK inhibitor, fostamatinib has recently been recognized as a potential therapy for acute respiratory distress syndrome (ARDS) in patients with severe COVID-19." (PMID 37631077, 2023).
alcoholic hepatitis (1 paper, 2022). Acute hepatitis resulting from ingestion of alcohol. "Therefore, the effective inhibition of SYK activation is also considered as a novel strategy against alcoholic hepatitis." (PMID 36568669, 2022). "The activation of SYK can be induced by alcohol, and SYK phosphorylation also joins in the regulation of immune cell-driven liver inflammation and holds a central modulatory position in multiple proinflammatory signaling pathways in alcoholic hepatitis." (PMID 36568669, 2022).
anaphylaxis (1 paper, 2023). An acute hypersensitivity reaction that occurs from exposure to an allergen. "Additional evidence is documented suggesting that IRE1 RNAase activity may lead to activation of spleen tyrosine kinase (SYK) as inhibition of the RNAase domain reduced both XBP1 and SYK activation in a mouse model of anaphylaxis." (PMID 37107600, 2023).
B-cell precursor acute lymphoblastic leukemia (1 paper, 2024). "Autophagy inhibition, spleen tyrosine kinase (SYK), and IGF2BP1 are potential future therapeutic targets for ETV6::RUNX1-driven B-cell precursor acute lymphoblastic leukemia due to their roles in ETV6::RUNX1 cell survival and prognosis." (PMID 38811988, 2024).
bladder urothelial carcinoma (1 paper, 2021). "On the contrary, the SYK gene was downregulated in bladder urothelial carcinoma (BLCA), kidney renal clear cell carcinoma (KIRC), kidney renal papillary cell carcinoma (KIRP), prostate adenocarcinoma (PRAD), cutaneous skin melanoma (SKCM), and thyroid carcinoma (THCA)." (PMID 34575665, 2021).
brachydactyly (1 paper, 2021). A disease characterized by the presence of brachydactyly, including syndromic and non-syndromic forms. "Of the genes associated with congenital abnormality, four genes (HDAC4, PTCH1, EHMT1, SYK) were associated with brachydactyly, according to the DisGeNET database." (PMID 34246298, 2021).
cervical cancer (1 paper, 2025). A primary or metastatic malignant neoplasm involving the cervix. "The results demonstrate that 125I seed radiotherapy significantly inhibits the invasion and migration of cervical cancer cells by upregulating the HSF1/PU.1/SYK signaling pathway." (PMID 40399470, 2025). "By upregulating the HSF1/PU.1/SYK signaling pathway, 125I seeds not only restrain the growth and proliferation of cervical cancer cells but also markedly diminish tumor invasion and migration." (PMID 40399470, 2025). "Finally, we used the subcutaneous xenograft tumor experiment in nude mice to verify that 125I particle radiotherapy inhibits the progression of cervical cancer by promoting the HSF1/PU.1/SYK signaling pathway." (PMID 40399470, 2025).
cholestasis (1 paper, 2023). Impairment of the bile flow caused by obstruction within the liver, or outside the liver in the bile duct system. "Intriguingly, a SYK inhibitor was predicted to be a promising agent for UDCA-refractory cholestasis by CMap analysis." (PMID 37229242, 2023). "Taken together, cholestasis-stimulated SYK may affect the efficacy of UDCA by regulating immune-related pathways and reducing monocyte infiltration." (PMID 37229242, 2023). "Furthermore, we demonstrated that impaired SYK expression and monocyte infiltration were potentially associated with UDCA nonresponse, indicating a promising therapeutic target for cholestasis." (PMID 37229242, 2023).
chronic kidney disease (1 paper, 2025). Impairment of the renal function secondary to chronic kidney damage persisting for three or more months. "The SYK inhibitor, entospletinib prevents non-resolving renal inflammation and enhances repair pathways in the kidney following acute injury limiting the development of chronic kidney disease." (PMID 40857403, 2025).
chronic multifocal osteomyelitis (1 paper, 2021). "Spleen tyrosine kinase (SYK) performs a key role upstream of caspase-1 and caspase-8, primarily upregulating NF-κB and IL-1β signaling in Pstpip2cmo mice, and induction of chronic multifocal osteomyelitis (CMO)." (PMID 33215255, 2021).
co-infection (1 paper, 2020). "This is particularly important as advances in healthcare that ultimately result in inhibition of the host immune response (e.g. SYK inhibitors) will facilitate the emergence of new pathogens and co-infection by diverse pathogens that are well adapted to thrive in the immunocompromised host." (PMID 32068530, 2020).
crescentic glomerulonephritis (1 paper, 2020). A histopathologic term for a pattern of diseases characterized by extensive crescent formation in the glomeruli; patients present clinically with rapid deterioration of renal function, and possible progression to end-stage renal failure within weeks or months. "The findings reported here are consistent with our previous work showing that SYK inhibition with fostamatinib is effective in both preventing and treating established crescentic glomerulonephritis in anti–glomerular basement membrane disease models." (PMID 32305129, 2020).
demyelinating disease (1 paper, 2023). A broad group of disorders that affect the myelin sheaths that cover the neurons. "Lastly, as it pertains to microglial response in demyelinating disease, spleen tyrosine kinase (SYK) has been shown to play a neuroprotective role." (PMID 36982999, 2023).
dependent (1 paper, 2017). "This work in particular implicates mercury interference with the BCR dependent phosphorylation of specific SYK phosphosites in the development of mercury dependent immunotoxicity." (PMID 28716125, 2017).